HDAC6 (histone deacetylase 6)
Diseases named in the same sentence as HDAC6 in open-access papers (continued):
Sharing a sentence is not in itself a finding about the gene and the disease.
melanoma (continued). "HDAC6 is overexpressed in numerous cancers, including gastric cancer, glioblastoma, and melanoma." (PMID 34746935, 2021). "In addition, class-specific or class-selective histone deacetylase 6 (HDAC6) inhibition downregulated the expression of LAG-3 in T cells from melanoma patients, thus alleviating T cell suppression." (PMID 34067904, 2021). "In preclinical studies with melanoma murine models, HDAC6 inhibitors exhibited antitumor activity and immune marker modulation to increase melanoma immunogenicity through major histocompatibility complex Class I (MHC-I) and tumor antigen expression on melanoma cells." (PMID 31963449, 2020). "Meanwhile, HDAC6 is essential in the regulation of PD-L1 expression in melanoma cells." (PMID 31652644, 2019). "As reported, HDAC6 is highly expressed in malignant melanoma." (PMID 30176876, 2018). "Melanoma cells, compared to other tumor cell types, expressed higher protein levels of HDAC6 which may explain melanoma sensitivity to HDAC inhibitors." (PMID 28146421, 2017). "HDAC6 has been shown to be essential for melanoma cell cycle progression." (PMID 29137331, 2017). "Finally, we tested HDAC5 and HDAC6 expression and sub-location in clinical melanoma tissues and tumor adjacent tissues." (PMID 26747087, 2016). "Furthermore, we knocked down HDAC5 or HDAC6 in A375 cells and demonstrated that both HDAC5 and HDAC6 contributed to the proliferation and metastasis of melanoma cells." (PMID 26747087, 2016). "Knockdown of HDAC5 or HDAC6 can cause apoptosis and cell cycle arrest, meanwhile, suggesting that there is no functional redundancy in A375 melanoma cells between HDAC5 and HDAC6." (PMID 26747087, 2016). "While class I HDAC are reported to be involved in MHC class I expression, the class IIb HDAC6 seems also involved as specific inhibition of HDAC6 via genetic means or with small molecule inhibitors Nexturastat A or Tubastatin A increased MHC class I expression in melanoma." (PMID 26426052, 2015). "Cell cycle arrest may partially explain the induction of cell growth inhibition of HDAC6 knockdown in melanoma cell line A375.S2." (PMID 25774669, 2015). "In the present study, HDAC6 expression was up-regulated in melanoma tissues and cell lines." (PMID 25774669, 2015). "In compared with NC siRNA cells, fluorescence intensities of cells were significantly increased, indicating that silencing of HDAC6 could initiate apoptosis of human melanoma A375.S2 cells." (PMID 25774669, 2015). "The higher expression of HDAC6 in three melanoma cell lines (A375.S2, SK-MEL-28 and HT-144), compared with a normal skin epithelium cell line (HaCaT) or compared with normal human epidermal melanocytes (PIG1), was examined (**P < 0.01 and ***P < 0.001, respectively)." (PMID 25774669, 2015). "Therefore, our results demonstrated that HDAC6 expression was up-regulated in melanoma tissues and cell lines." (PMID 25774669, 2015). "Therefore, we demonstrated the potential of silencing HDAC6 expression in melanoma cells would be expected to predominantly be an anticancer therapeutic agent." (PMID 25774669, 2015). "Considering the high expression level of HDAC6 in melanoma tissue and cells and the specificity of HDAC6-siRNA for the inhibition of melanoma cell, silencing HDAC6 expression may be considered as a novel therapeutic approach to treat melanoma." (PMID 25774669, 2015). "Altogether, our results suggest that HDAC6 controls SIRPα expression in macrophages and melanoma patients and that HDAC6i can be used to downregulate the expression of anti-phagocytic signals and upregulate pro-phagocytic signals, which may enhance the phagocytic capacity of macrophages." (PMID 38414061, 2024). "Interestingly, in a melanoma mouse model, HDAC6 inhibitor Nexturastat A given in conjunction with anti-PD-1 antibodies significantly impaired tumor growth by causing a decrease in the anti-inflammatory phenotype of macrophages and increased infiltration of CD8+ T cells and NK cells into the TME." (PMID 34575678, 2021).
melanoma (continued). "Another study showed that long-term treatment with the BRAFi PXL4032 on sensitive BRAF mutant melanoma cell lines induced senescent resistant clones that portrayed a stem cell-like phenotype and had an aberrant expression of multiple epigenetic modifiers such as HDAC6." (PMID 34944799, 2021). "Interestingly, HDAC5 and HDAC6 may influence melanoma cell proliferation through different pathways." (PMID 26747087, 2016). "Thus, the effects of siRNA-mediated knockdown of HDAC6 were investigated in malignant melanoma." (PMID 25774669, 2015). "Studies in melanoma reveal that low expression of MIIP and high expression of its downstream molecule HDAC6 correlate with poorer overall survival, with a positive correlation between HDAC6 and PD-L1 protein expression." (PMID 40573881, 2025). "For example, in squamous cell NSCLC elevated levels of histone deacetylases (HDAC), such as HDAC3 and HDAC6, are detected, that are reported to upregulate PD-L1 expression by STAT3 signalling pathway in melanoma, osteosarcoma, and pancreatic cancer." (PMID 38541208, 2024). "HDAC6 downregulation decreased the expression levels of MDR1 and tubulin β3 in anti-cancer drug-resistant melanoma cells." (PMID 36076996, 2022). "Conversely, using HDAC6-selective inhibitors induced a decrease in the frequency, FOXP3 expression, and suppressive function of Tregs on T-cells from melanoma patients treated in ex vivo cultures." (PMID 35008230, 2021). "Since HDAC6 regulates PD-L1 expression in melanoma cells through STAT3 signaling, HDAC6 inhibitors can be used to decrease PD-L1 expression, thus reversing this resistance." (PMID 34944799, 2021). "Histone deacetylase 6 (HDAC6) is a unique isoform of the HDAC family, which is overexpressed in some cancers, such as bladder cancer, malignant melanoma, and lung cancer." (PMID 32888405, 2020). "Here, we investigated the ability of histone deacetylase 6 (HDAC6)-selective inhibitors to decrease immunosuppression and enhance immune function of melanoma patient T-cells in ex vivo cultures." (PMID 30728070, 2019). "Our results demonstrate that the HDAC6-selective inhibitors ACY-1215 and ACY-241 alter melanoma patient T-cell phenotypes and function ex vivo at concentrations achievable in human patients, resulting in enhanced effector function without impacting viability." (PMID 30728070, 2019). "In human melanoma cell lines, melanoma antigens gp100, MART1, TYRP1, and TYRP2 were upregulated at the mRNA level following treatment with HDAC6 inhibitors (Nexturastat A or Tubastatin A)." (PMID 30176876, 2018). "There is at present an open clinical trial combining the HDAC6 specific HDAC inhibitor ACY-241 with Ipilimumab (anti-CTLA4) and Nivolumab (anti-PD-1) for melanoma (NCT02935790)." (PMID 29137331, 2017). "Here, we showed the expression levels of all 11 HDACs in multiple melanoma cells comparing with normal skin cells and found that HDAC5 and HDAC6 have lower expression levels in normal tissues but much higher expression in A375 and A2058 cells." (PMID 26747087, 2016). "This study provided evidence for the first time that melanoma specifically overexpressed HDAC5 and HDAC6." (PMID 26747087, 2016). "To clarify the roles of HDAC5 and HDAC6 in melanoma progression, we designed three shRNA sequences for knocking down HDAC5 or HDAC6." (PMID 26747087, 2016). "Thus, we suggest that HDAC5 and HDAC6 may contribute to the occurrence of melanoma." (PMID 26747087, 2016). "Histone deacetylase 6 (HDAC6), belonging to the IIb class HDAC family, mainly localizes in the cytoplasm and exhibits overexpression characteristics in various malignant tumors, including lung cancer and melanoma." (PMID 40699737, 2025). "Independent from vemurafenib resistance, the curcumin-harmine-isovanillin combination drug GZ17-6.02 upregulated class I MHCA and suppressed PD-L1 in PDX BRAFV600E melanoma cells, which was mediated by the downregulation of several HDACs (HDAC3, HDAC5, HDAC6, HDAC7, and HDAC8)." (PMID 39935431, 2025).
melanoma (continued). "Therefore, after assessing the modulatory role of HDAC6 on macrophage phenotype, we evaluated the effects of HDAC6 inhibition in modulating the CD47/SIRPα axis in melanoma cells and macrophages." (PMID 38414061, 2024). "In melanoma models, HDAC6 inhibitors had a more significant inhibitory effect on tumor growth in C57BL/6 mice than in immunodeficient mice, which demonstrates that the antitumor effect of HDAC6 inhibitors requires an intact host immune system." (PMID 36270986, 2022). "XP5, an inhibitor of HDAC6, in combination with a small-molecule PD-L1 inhibitor (NP19) synergistically enhanced anti-tumor immune responses by increasing tumor-infiltrating lymphocytes while decreasing PD-L1 expression in melanoma." (PMID 36076996, 2022). "Another study also reported that HDAC6 can recruit and activate the signal transducer and activator of transcription 3 (STAT3), which increases the expression of PD-L1 through STAT3-mediated activation of the PD-L1 promoter in melanomas." (PMID 35585975, 2022). "As revealed in another study, HDAC6 inhibition could suppress the T cell expression levels of PD-1, TIM-3 and LAG-3, relieving T cell suppression in melanoma patients." (PMID 35585975, 2022). "Previously, it was reported that the lethality of pazopanib could be significantly enhanced via knockdown of [HDAC6 + HDAC2] or [HDAC6 + HDAC10], while the knockdown of [HDAC6 + HDAC1] or [HDAC6 + HDAC3] is less effective in melanoma cells." (PMID 36224606, 2022). "While NextA has been shown to specifically inhibit HDAC6 activity, these effects have not been sufficient to generate complete tumor regression in melanoma, which can be achieved using PTT." (PMID 31963449, 2020). "To answer this question, we challenged wild-type C57BL/6 mice (fully functional HDAC6 activity) with SM1 melanoma cells lacking HDAC6 (HDAC6KD)." (PMID 30992475, 2019). "In addition, HDAC6 inhibition diminished the expression of SIRPα, increased the expression of other pro-phagocytic signals in macrophages, and downregulated CD47 expression in mouse and human melanoma cells." (PMID 38414061, 2024). "In addition, our data, knocking down individual HDAC proteins, argues that a highly specific HDAC6 inhibitor in melanoma cells is unlikely to effectively modulate the expression of PD-L1, PD-L2, MHCA or ODC in a manner like AR42 or valproate." (PMID 29137331, 2017). "However, western blots did not demonstrate the specific location of HDAC5 or HDAC6 in melanoma tissues." (PMID 26747087, 2016). "HDAC6 binds to Tyrosine-protein phosphatase non-receptor type 1 (PTPN1), activates extracellular signal-regulated kinase 1/2 (ERK1/2), inhibits apoptosis, and promotes melanoma cell proliferation." (PMID 32626712, 2020).
ovarian carcinoma (45 papers, 2007 to 2025). A malignant neoplasm originating from the surface ovarian epithelium. "In ovarian cancer and hepatocellular carcinoma, high HDAC6 is associated with advanced clinical stage, higher number of tumours, vascular and intrahepatic invasion, and metastasis, which are related to poor prognosis, respectively." (PMID 39941046, 2025). "Lastly, a study found that HDAC6 (Histone deacetylase 6) was upregulated in ovarian cancers with ARID1A mutations." (PMID 40429787, 2025). "Vorinostat is a histone deacetylase inhibitor (HDACi) that suppresses HDAC6 expression, thereby disrupting the ARID1A6488delG/HDAC6/IL-10 signaling pathway implicated in endometriosis-associated ovarian carcinoma (EAOC)." (PMID 40330466, 2025). "The dependence on HDAC6 activity in ARID1A-mutated ovarian cancer cells has been reported to be correlated with direct transcriptional repression of HDAC6 by ARID1A as HDAC6 inhibition selectively promoted apoptosis of ARID1A-mutated cells." (PMID 31731647, 2019). "Other studies have shown the essential role for histone deacetylase 8 (HDAC6) in ARID1A-mutated ovarian cancers: inhibition of HDAC6 activity in these tumors inhibited cell growth and promoted apoptosis." (PMID 29389895, 2018). "The same group showed earlier that HDAC6 activity is essential in ARID1A-mutated ovarian cancers." (PMID 36980292, 2023). "Additionally, HDAC3 has a role in inflammation whereas HDAC4 facilitates proliferation, invasion potential and migration of ovarian cancer cells by suppressing p21, while HDAC6 is over-expressed in ARID1A-mutated EOCs." (PMID 36034650, 2022). "Indeed, in some human tumors, the overexpression of HDAC6 is associated with more advanced tumor stages and higher tumor invasiveness, so the survival rate is low in cholangiocarcinoma, ovarian cancer, and acute myeloid leukemia (AML)." (PMID 33959656, 2021). "Ovarian cancer cells overexpress HDAC6, and selective HDAC6 inhibitors have been considered potential new drugs for ovarian cancer either alone or in combination with other anticancer agents." (PMID 40649308, 2025). "Recent studies also revealed that overexpression of HDAC6 correlates with the progression of various cancers, such as ovarian cancer, breast cancer, lung cancer, and prostate cancer." (PMID 40649308, 2025). "The MTT assay was conducted to determine the cell viability of ES-2 ovarian cancer cells treated with 46 potential selective HDAC6 inhibitors at 1.25 μM for 72 h." (PMID 40649308, 2025). "Some studies have reported that HDAC6 inhibitors can enhance the activity of Taxol in ARID1A-null ovarian cancer cells and tumor models, partly due to the disruption of microtubule dynamics." (PMID 40649308, 2025). "HDAC6 expression is upregulated in low-grade and high-grade ovarian cancers, oral squamous cell carcinoma, hepatocellular carcinoma, and acute myeloid leukaemia (AML) and is associated with increased chemotherapy resistance in acute lymphoblastic leukaemia." (PMID 39941046, 2025). "HDAC6 has recently emerged as a promising target for ovarian cancer treatment since it has been found to overexpress in ovarian cancer and is also involved in vital cancer progression processes." (PMID 40649308, 2025). "Studies have found elevated HDAC6 in ovarian cancer, which helps the cancer cell to develop chemoresistance and possible metastasis such as anchorage-independent proliferation, cell migration, and invasion." (PMID 40649308, 2025). "Taken together, our novel selective HDAC6 inhibitor 25253 demonstrated a synergic effect when combined with Taxol not only in ARID1A-null TOV21G cells but also in ARID1A wild-type ES-2 ovarian cancer cells." (PMID 40649308, 2025). "For instance, PCI‐34051 has been shown to induce caspase‐dependent apoptosis in T‐cell lymphomas and leukaemias, and its combination with ACY‐241 (a selective HDAC6 inhibitor) synergistically enhances apoptosis in ovarian cancer cells." (PMID 39317961, 2024).
ovarian carcinoma (continued). "In ovarian cancer cells, 33 evokedenhanced effects on cell viability compared to single or combinationtreatment with the unconjugated Sirt2 and HDAC6 inhibitors." (PMID 37902787, 2023). "It is reported that HDAC6 is required for malignant growth of ovarian cancer cells and upregulated in tumors compared to benign lesions." (PMID 36467091, 2022). "Overexpression of HDAC6 has also recently been presented as a favorable prognostic marker of ovarian cancer." (PMID 35955780, 2022). "Specifically, HDAC6 participates in cell proliferation, metastasis, invasion, and mitosis in tumors, and is overexpressed in ovarian cancer, bladder cancer, lung cancer, and colon cancer." (PMID 35955780, 2022). "These aloxyurea derivatives, which contained structural similarity with ricolinostat, depicted selective inhibition of HDAC-1 and HDAC-6 over other HDACs and also displayed satisfactory inhibitory potential against ovarian cancer cells A2780 and A2780CisR." (PMID 36034650, 2022). "For example, inhibition of HDAC6 enhances antitumor immune signaling and reduces tumor load in ovarian cancer." (PMID 34485153, 2021). "In ovarian cancer, HDAC6 expression levels were shown to be higher in low-grade and high-grade cancers compared to benign lesions." (PMID 33322608, 2020). "In a similar way, a HDAC6 inhibitor (riconilostat) blocked the immune checkpoints when it was combined with anti-PD-L1 therapy in ovarian carcinoma cell lines and in in vivo models." (PMID 33024443, 2020). "In summary, we demonstrated, for the first time, that HDAC6 over-expression in ovarian cancers is a favorable prognostic marker." (PMID 33322608, 2020). "We provide evidence to suggest that inhibition of HDAC6 catalytic activity has limited efficacy as a monotherapy in ovarian cancers." (PMID 33322608, 2020). "Combining nexturastat A (selective HDAC6 inhibitor) with 5-azacytidine (DNMTi) has been described recently as a novel approach for ovarian cancer." (PMID 33024443, 2020). "While HDAC6 can be over-expressed in ovarian cancer cells, few studies have assessed the contribution of HDAC6 expression to HGSOC prognosis." (PMID 33322608, 2020). "This study investigated HDAC6 tumor expression by immunohistochemistry in high-grade serous ovarian cancer (HGSOC) tissue samples and a meta-analysis of HDAC6 gene expression in ovarian cancer from publicly available data." (PMID 33322608, 2020). "HDAC6 knockdown produced a robust inhibition of HGSOC migration, in which we next examined the impact of pharmacological HDAC6 inhibition on the migratory properties of ovarian cancer cells in a trans-well setting." (PMID 33322608, 2020). "In conclusion, our results indicate that the over-expression of HDAC6 is a favorable prognostic marker in the HGSOC ovarian cancer subtype and highlights HDAC6 as a potential therapeutic target for HGSOC." (PMID 33322608, 2020). "Recently, ovarian cancer cells carrying ARID1A mutation showed higher sensitivity to SAHA and ACY1215 treatment, through inhibition of HDAC2 and HDAC6 activity respectively." (PMID 31165775, 2019). "In acute lymphoblastic leukemia, oral squamous cell carcinoma, ovarian cancer, and hepatocellular carcinoma, HDAC6 acts as a tumor inducer: its overexpression is correlated with a more advanced stage and increased tumor aggressiveness." (PMID 30050135, 2018).